FOXJ3 (forkhead box J3)
Description:
Transcriptional activator of MEF2C involved in the regulation of adult muscle fiber type identity and skeletal muscle regeneration (By similarity). Plays an important role in spermatogenesis (By similarity). Required for the survival of spermatogonia and participates in spermatocyte meiosis (By similarity).
Synonyms: KIAA1041
Tractability: PROTAC: ubiquitination databases record sites on it.
Gene: Protein-coding gene on chromosome 1 (42,176,535 to 42,335,913, reverse strand). Ensembl gene ENSG00000198815.
Subcellular location: Nucleus
Subcellular location (Human Protein Atlas): Nuclear speckles; Nucleoplasm; Vesicles
Gene Ontology:
Molecular function: DNA-binding transcription activator activity, RNA polymerase II-specific; protein binding; sequence-specific DNA binding; sequence-specific double-stranded DNA binding; DNA-binding transcription factor activity, RNA polymerase II-specific; RNA polymerase II cis-regulatory region sequence-specific DNA binding; DNA-binding transcription factor activity
Biological process: positive regulation of transcription by RNA polymerase II; male meiosis I; regulation of transcription by RNA polymerase II; spermatogenesis; regulation of DNA-templated transcription
Cellular component: chromatin; nucleus
Genetic constraint (gnomAD): Loss-of-function variants: 6 observed, 28.31 expected, observed/expected ratio (o/e) 0.21, 90% interval 0.12 to 0.42. The upper end of that interval is the gene's LOEUF score, 0.42, which puts it in group 1 of 6, group 1 being the genes least tolerant of losing a copy. Missense variants: 353 observed, 423.43 expected, observed/expected ratio (o/e) 0.83, 90% interval 0.76 to 0.91. Synonymous variants: 147 observed, 152.96 expected, observed/expected ratio (o/e) 0.96, 90% interval 0.84 to 1.1.
Homologues: Orthologues: chimpanzee FOXJ3 (99% identical), macaque FOXJ3 (99% identical), dog FOXJ3 (97% identical), pig FOXJ3 (97% identical), mouse Foxj3 (95% identical), rabbit FOXJ3 (89% identical), tropical clawed frog foxj3 (74% identical), rat Foxj3 (73% identical), guinea pig Foxj3 (21% identical). Paralogues in human: FOXJ2 (38% identical), FOXC1 (16% identical), FOXK2 (16% identical), FOXA2 (16% identical), FOXK1 (16% identical), FOXA1 (15% identical), FOXC2 (15% identical), FOXM1 (14% identical), FOXI3 (14% identical), FOXD3 (14% identical), FOXA3 (14% identical), FOXD1 (14% identical), and 29 more.
Diseases named in the same sentence as FOXJ3 in open-access papers:
FOXJ3 is named in the same sentence as 14 diseases in open-access papers, as found by Europe PMC text mining. Sharing a sentence is not in itself a finding about the gene and the disease. The quoted sentences say what the papers report.
lung cancer (6 papers, 2018 to 2025). A malignant neoplasm involving the lung. "FOXJ3 plays a role in cell proliferation, migration, and invasion in lung cancer by MiR-517a-3p regulation." (PMID 40001606, 2025). "Overexpression of miR-517a-3p in lung cancer cell lines has been found to increase lung cancer cell proliferation, migration and invasion abilities through inhibition of forkhead box J3 (FOXJ3) expression." (PMID 32015692, 2020). "FOXJ3 is a transcription factor that is down-regulated in colorectal cancer and lung cancer." (PMID 33868377, 2021). "In non‐small cell lung cancer, miRNA inhibits the expression of FOXJ3 by binding to the 3′UTR of FOXJ3, affecting the antiproliferative effect of FOXJ3." (PMID 39907030, 2025).
colorectal cancer (4 papers, 2019 to 2025). A primary or metastatic malignant neoplasm that affects the colon or rectum. "In colorectal cancer, miR-27a and FOXJ3 dysregulate the mitochondrial dynamics." (PMID 40001606, 2025).
breast carcinoma (3 papers, 2019 to 2025). "In breast cancer, FOXJ3 regulation of snail expression has an influence on cell proliferation and migration." (PMID 40001606, 2025). "The up-regulation of FOXJ3 in multiple types of cancers and the link between THRA and the breast cancer prognostic prediction suggest oncogenic functions of these two transcription factors, which is opposite to that of 7SK." (PMID 33868377, 2021).
chronic myelogenous leukemia (1 paper, 2024). "With SPI1 appearing to be a specific modulator in macrophages, K-562 (human chronic myelogenous leukemia cell line) cells instead rely upon multiple TFs, from AP-1 to FOXJ3." (PMID 38343549, 2024).
colon cancer (1 paper, 2021). "For instance, in SW48 and HCT116 colon cancer cells, an inverse correlation was identified between the expression of miR-517a and the forkhead box J3 (FOXJ3) tumor suppressor." (PMID 34957087, 2021).
idiopathic pulmonary arterial hypertension (1 paper, 2025). A sporadic form of pulmonary arterial hypertension (PAH) characterized by elevated pulmonary arterial resistance leading to right heart failure. "In addition, the expression of CITED2 and FOXJ3 also decreased in both the patients with idiopathic pulmonary arterial hypertension (iPAH) and the human PASMCs exposed to hypoxia." (PMID 39907030, 2025).
stomach adenocarcinoma (1 paper, 2025). "Forkhead box protein J3 (FOXJ3) expression is positively correlated with stomach adenocarcinoma and involved in histone modification, the TGF-β signaling pathway, and chromatin organization." (PMID 41440381, 2025).
tumor (5 papers, 2021 to 2025). "Altogether, our results suggest a putative functional involvement of the transcriptional factors FOXJ3 and THRA in the 7SK-associated gene expression control and tumor migration in TSCC." (PMID 33868377, 2021). "The disclosure that the miR-27a/FOXJ3 axis is pivotal in modulating mitochondrial functionality adds to our understanding on the molecular events underlying tumorigenesis and may pave the way for further studies aimed at restraining tumor growth by stimulating mitochondrial activities." (PMID 34638478, 2021). "The miR-27a/FOXJ3 axis is a major actor in regulating mitochondrial homeostasis, and its discovery may contribute to therapeutic strategies aimed at restraining tumor growth by targeting mitochondrial activities." (PMID 34638478, 2021). "The knockdown of all transcription factors, except FoxJ3 and PBX3, attenuated the viability of tumor spheroids in response to cisplatin." (PMID 40860181, 2025). "Expression of several genes identified by usare known predictors of clinical outcome in different tumor types including ANXA1, FOXJ3 and CDC25 (Liuet al., 2019, 2020), among manyothers." (PMID 34617951, 2021). "Here, we identified 7SK acting as a novel tumor suppressor in TSCC, and suggested a putative functional involvement of FOXJ3 and THRA in 7SK-mediated TSCC progression." (PMID 33868377, 2021). "All in all, we have reported a tumor-suppressive role of 7SK in TSCC and suggested a putative functional involvement of FOXJ3 and THRA in 7SK-mediated TSCC progression." (PMID 33868377, 2021). "In addition, we have also identified a set of genes that are regulated in the opposite way by 7SK and FOXJ3/THRA, including four positive regulators in tumor migration (CXCL1, SYDE1, COL5A1, and HIF1A)." (PMID 33868377, 2021). "It would be of great interest to demonstrate whether a directly functional link between FOXJ3/THRA and 7SK is involved in 7SK-mediated genes and 7SK-mediated tumor progression events in the near future." (PMID 33868377, 2021).
cancer (3 papers, 2021 to 2025). A tumor composed of atypical neoplastic, often pleomorphic cells that invade other tissues. "By integrating patterns of FOX genes expression with anticancer drugs sensitivity, we speculated that six FOX genes, including FOXO3, FOXO1, FOXN3, FOXK2, FOXN2, and FOXJ3, might be important for the development and treatment of a wide range of cancers." (PMID 36292640, 2022). "Interestingly, the expression level of FOXJ3 was augmented in TSCC patients and previous reports of other cancer have suggested an oncogenic role of THRA." (PMID 33868377, 2021). "Interestingly, the augmented level of FOXJ3 in TSCC patients and previous reports on THRA in other cancers have suggested that these two factors may promote TSCC progression." (PMID 33868377, 2021).
FOXJ3 also shares sentences with these, for which no sentence is quoted: prostate carcinoma (2 papers); gastric cancer (1); leukemia (1); nervous system tumors (1); prostatic hyperplasia (1).